AXL (AXL receptor tyrosine kinase)
Diseases named in the same sentence as AXL in open-access papers (continued):
Sharing a sentence is not in itself a finding about the gene and the disease.
breast carcinoma (continued). "Not surprisingly then AXL has been implicated in breast cancer metastasis." (PMID 32148495, 2020). "Furthermore, AXL was described as a resistance factor for HER2 therapeutics in breast cancer." (PMID 29325228, 2018). "This study explores the involvement of AXL and hedgehog signaling in maintaining stemness and contributing to trastuzumab resistance in HER2-positive breast cancer." (PMID 41900890, 2026). "We found that SKBR3 breast cancer cells experienced TKI‐induced AXL upregulation, as measured by both protein and mRNA levels, and decreased pERK rebound in response to AXL inhibition." (PMID 39395205, 2025). "This cooperation between AXL and MERTK has been shown to accelerate the growth of breast cancer cells by combining oncogenic signaling and evading host antitumor immunity." (PMID 39924521, 2025). "AXL mRNA expression levels were relatively low in hormone-positive and HER2-positive breast cancer cells lines." (PMID 41009462, 2025). "In HER2-positive breast cancer cells, AXL physically interact with HER2, facilitating AXL’s stability and recruitment to the cell surface." (PMID 39924521, 2025). "CAR T cell-based therapy for breast cancer also targets RTK, including AXL, hepatocyte growth factor receptor (HGFR), and receptor tyrosine kinase-like orphan receptor 1 (ROR1)." (PMID 39755633, 2025). "Our data also evidenced that some YAP/TAZ target genes, such as NF2, AXL, SOX2 and BIRC5, were regulated by Bcl-2 specifically in breast carcinoma model." (PMID 38755629, 2024). "Our proteomic analysis revealed proteomic profile alteration in MDA-MB-231 upon CB exposure that potentially led to breast cancer suppression, such as ZPR1/SHC1/MAPK-mediated cell proliferation and AXL/VAV2/RAC1-mediated cell motility pathways." (PMID 39527598, 2024). "Our results revealed the reduction in AXL expression, which was known as a regulator for epithelial-to-mesenchymal transition (EMT) of breast cancer." (PMID 39527598, 2024). "Interference with AXL leads to downregulation of HIF-1α, which, in turn, reduces EMT induced by hypoxia and enhances the immunotherapeutic responses in HER2 breast cancer." (PMID 37328828, 2023). "AXL also induces the upregulation of ZEB1 (zinc finger E-box binding homeobox 1) transcription and mediates the drug resistance of breast cancer to doxorubicin through the same pathway." (PMID 37328828, 2023). "Our previous studies have shown that the Se/FO combination treatment increases the therapeutic efficacy of anti-cancer agents against breast cancer via the dose-dependent downregulation of TGF-β/TβR-2, AXL/Gas6, and β-catenin signaling." (PMID 36547898, 2022). "As an immune evasion mechanism, AXL signaling was shown to increase surface expression of MHC-class I molecules and PDL-1 in lung, renal and breast cancer cell lines." (PMID 35967396, 2022). "AXL was also shown to regulate HIF-1α levels, thus contributing to the hypoxic response in HER2+ breast cancer cells." (PMID 35158733, 2022). "Previous studies have also reported that Se/FO supplements target EGFR/TβR/AXL/PI3K/Akt/mTOR signaling and therefore increase the apoptotic efficacy of anti-cancer agents in breast-cancer-bearing mice and NSCLC cells." (PMID 36547898, 2022). "Using the RNA-Seq expression data and proteome data generated from Cancer Cell Line Encyclopedia (CCLE), we plotted the expression level of AXL in 27 breast cancer cell lines composed of 15 TNBC, 4 HER+ and 8 ER+ luminal A and B breast cancer cell lines." (PMID 34439388, 2021). "Induction of EMT in the breast cancer cell line, MCF10A, by Slug and the oncogenic H-Ras, induces vimentin overexpression, which in turn leads to AXL expression and activation." (PMID 34638469, 2021).
breast carcinoma (continued). "AXL-CAR-T cells were co-cultured with the AXL-positive breast cancer cell lines (MDA-MB-231, 786-0, 769-P, Panc1, and MIAPaca2) and the AXL-negative breast cancer cell line, MCF-7." (PMID 34729098, 2021). "Goyette and colleagues had also shown that AXL is necessary for inducing TGFβ-mediated EMT, migration, and metastatic spread which confers resistance to anti-HER treatments in a breast cancer model." (PMID 33570712, 2021). "In human breast cancer epithelial cells, SLUG and SNAIL increase the expression of AXL, which indicates that AXL, as an important factor of the epithelial-mesenchymal transition (EMT) process, is involved in metastasis in cancer cells." (PMID 33954117, 2021). "The AXL/Gas6 pathway is a potent EMT inducer and a metastatic phenotype promoter, that has been proposed as a pharmacological target in breast cancer for its role in controlling the invasive phenotype of cancer cells." (PMID 34452195, 2021). "Basing our research on these studies, we set out to investigate the role of AXL in invasion and migration of MDA-MB-231 breast cancer cells." (PMID 33374832, 2020). "Recently, it was found that AXL and PEAK1 are co-expressed in aggressive basal B breast cancers where AXL is required for invasion." (PMID 32681075, 2020). "Lastly, miR-34a inhibits AXL expression and regulates VM formation, cell invasion, and migration in MDA-MB-231 breast cancer cells." (PMID 33374832, 2020). "In a model of TNBC breast cancer, xenografts of MDA-MB-231 cells showed reduced tumor growth with AXL knockdown." (PMID 32148495, 2020). "In a mouse model of radioresistant breast cancer, MMTV-PyMT tumors selected for resistance to radiation therapy, AXL knockout reduced tumor growth compared to control tumors." (PMID 32148495, 2020). "AXL, a member of the TYRO-3, AXL and MER (TAM) subfamily, is, today, considered a predictive and prognostic biomarker in many tumor contexts, primarily breast cancer." (PMID 33182542, 2020). "AXL is reported to induce EMT and self-renewal in breast cancer cells and chronic myelogenous leukemia CSCs18,19, and has a crucial role in the CSCs of various cancers." (PMID 32051483, 2020). "As the concentration of VP increased, the expressions of AXL and CYR61 proteins in different subtypes of breast cancer cells were downregulated." (PMID 33121449, 2020). "Stimulation of AXL and these subsequent downstream pathways appears to be ligand-independent in HER2+ breast cancer." (PMID 32148495, 2020). "AXL and HER2 pharmacological inhibition determines a reduction in metastasis in HER2-positive breast cancer mice." (PMID 33182542, 2020). "Next, to determine the mechanism of AXL in VM formation and invasiveness of breast cancer cells, we examined the expression of EMT markers in MCF-7/AXL stable cells." (PMID 33374832, 2020). "AXL knockdown led to a drastic reduction in VM formation in MDA-MB-231, BT-549, and HS578T breast cancer cells, suggesting the potential role of AXL as a mediator of VM formation." (PMID 33374832, 2020). "In fact, AXL and MET are known oncogenes, and different studies show that they have roles in progression of breast cancer." (PMID 30386383, 2018). "EMT is an important process in cancer progression and metastasis, and AXL is an inducer of EMT-related proteins, such as N-cadherin, Snail, Slug, and vimentin in breast cancer cells." (PMID 29259259, 2017). "Over-expression of AXL has been shown to be a novel mechanism of acquired resistance to HER2-targeted agents in lapatinib-resistant, HER2-positive breast cancer clones." (PMID 27172793, 2016). "Treatment with an AXL inhibitor, MP470 (an AXL, PDGFRa, ckit inhibitor; SuperGen, Dublin, CA, USA) reduced the ability of breast cancer stem cells to form mammospheres and improved tumor cell sensitivity to chemotherapy." (PMID 27834845, 2016).
breast carcinoma (continued). "To characterize the expression of AXL in vitro, we analyzed the expression of the tyrosine kinase, EMT (CDH1 and VIM), and basal (EGFR, KRT5, and KRT6A) markers in 15 breast cancer cell lines by quantitative real-time PCR (qRT-PCR)." (PMID 28721387, 2016). "Taken together, these results indicate that E1A reduces AXL expression and consequently results in enhanced EGFR-TKI sensitization of breast cancer cells both in vitro and in vivo." (PMID 27590506, 2016). "AXL expression has been found to be induced by epithelial-mesenchymal transition (EMT) and to correlate with induction of EMT in breast cancer and in ESCC." (PMID 27172793, 2016). "In breast cancer cells, DN10764 inhibited cell proliferation and GAS6-mediated AXL signaling, consequently resulting in suppressed migration and invasion." (PMID 27829217, 2016). "Taken together, our findings suggest that a combination of E1A gene therapy or an AXL inhibitor and EGFR-TKI will improve treatment of breast cancer." (PMID 27590506, 2016). "In breast cancer cells, DN10764 was found to inhibit cell proliferation and GAS6-mediated AXL signaling pathways, resulting in the suppression of migration and invasion." (PMID 27829217, 2016). "Among these, AXL and FUT1 were previously determined as the targets of miR-34a in non-small cell lung cancer, colorectal cancer and breast cancer." (PMID 25762634, 2015). "We and others have shown that Fra-1 promotes metastasis through various molecules: ADORA2B in breast cancer, MMPs in breast cancer and in lung epithelial cells, CD44 in mesothelioma, AXL in bladder cancer, FAK and EZH2 in colon cancer." (PMID 26646695, 2015). "Triple negative breast cancer (TNBC) cell lines that overexpress both EGFR and AXL appear to be more sensitive to AXL than EGFR inhibition." (PMID 25337673, 2014). "While the mechanism of AXL overexpression upon acquired resistance remains unclear in vivo, one study suggests that hypomethylation of the AXL promoter may play a role in AXL overexpression in ErbB2-positive breast cancer cells upon acquisition of resistance to the ErbB2 inhibitor, lapatinib." (PMID 25337673, 2014). "AXL and VIM are up-regulated together in migrating cells at monolayer wound edges and in breast carcinomas." (PMID 22570691, 2012). "The apoptotic genes SPP1 and SFRP1 are candidate tumor suppressors for various cancers; AXL gene is a proto-oncogene, and NOL3 (ARC, apoptosis repressor with CARD domain) is induced in human breast cancer and confers chemo- and radiation-resistance." (PMID 19455236, 2007). "CD8 T-sEVs containing AXL-siRNA (siAXL) loaded glutathione (GSH)-responsive PTX-poly-L-lysine (PTX-PLL; PP) prodrug micelle were found to induce paclitaxel (PTX) release which then destroyed breast cancer cells." (PMID 40560407, 2025). "In TNBC, the expression of AXL, PYK2, and PKCα correlates with stemness in breast cancer patients." (PMID 39924521, 2025). "Interestingly, AXL promotes EMT and therapeutic resistance in breast cancer by heterodimerizing with HER2, thereby inducing PI3K/Akt and MAPK signaling independent of its ligands." (PMID 39924521, 2025). "Despite these complexities, Reverse Phase Protein Arrays (RPPAs or RPLAs) analyses suggest that AXL and c-MET receptors exhibit crosstalk and may physically interact in breast cancer cells." (PMID 39924521, 2025). "Consistent with data in the literature, prolonged treatment with AXL inhibitors led to the partial restoration of epithelial morphology in mesenchymal breast cancer cells (not shown), repression of ZEB1 and reactivation of E-cadherin expression." (PMID 38172210, 2024). "Likewise, AXL-mediated NEDD9 phosphorylation is reported to recruit CrkII and thereby PEAK1, leading to altered FA dynamics in breast cancer cells." (PMID 37336884, 2023).
breast carcinoma (continued). "In head and neck and esophageal squamous cell carcinomas, AXL dimerizes with EGFR and activates PKC through PLCγ, and in breast cancer pharmacological inhibition, PKC resulted in decreased AXL expression, suggesting a feedback loop between AXL expression and PKC activation." (PMID 36835239, 2023). "Similarly, the activated HER2 forms a complex with AXL and activates AXL in a GAS6-independent manner, which accelerates epithelial-mesenchymal transition (EMT) and metastasis of breast cancer cells." (PMID 37328828, 2023). "In addition to KLF5, AXL is an EMT-induced regulator of cancer metastasis, controlled by Slug and Vimentin in breast cancer." (PMID 36042208, 2022). "However, ALKBH5 has been demonstrated to be an oncogene in glioblastoma through the modification of FOXM1, in breast cancer through m6A demethylation of NANOG, and in acute myeloid leukemia via AXL m6A modification." (PMID 35395767, 2022). "Moreover, inhibition of AXL decreases autocrine TGF-β signaling in hepatocellular carcinoma and impairs secretion of pro-angiogenic factors in breast cancer cells which in turn affects the function of endothelial cells in co-culture and in vivo." (PMID 35813203, 2022). "Although AXL inhibition prevents metastases, constitutive ectopic expression of AXL in metastatic breast cancer cells did not promote, but instead reduced the metastatic traits analysed in intravenous metastasis assay." (PMID 34638349, 2021). "In addition to the PI3K/Akt cascade, GAS6-induced AXL activation and triggers kinase signaling, including ERK and PEAK1, which contribute to the high invasiveness of breast cancer cells." (PMID 34831142, 2021). "The expression levels of AXL are extremely low in ER+ luminal and HER2+ breast cancer cell lines." (PMID 34439388, 2021). "A systematic investigation of AXL expression in a broader spectrum of breast cancer cell lines has not been performed." (PMID 34439388, 2021). "We performed immunoblotting to examine the expression levels of AXL in a subset of breast cancer cell lines including MCF10A, a spontaneously immortalized normal mammary gland epithelial cell line, HCC1954, a HER2+ breast cancer cell line and seven different TNBC cell lines." (PMID 34439388, 2021). "AXL, PYK2, and PKCα expression correlates with stemness signature in basal-like breast cancer patients, and their depletion in multiple mesenchymal TNBC cell lines markedly reduced the number of mammosphere-forming cells and cells harboring CSCs characteristic markers." (PMID 33785524, 2021). "For example, AXL has been shown to interact with HER2 in HER2+ breast cancer, but this receptor is not overexpressed in TNBC." (PMID 32148495, 2020). "Breast cancer cells with a high AXL expression formed VM, but those with a low AXL expression did not." (PMID 33374832, 2020). "This clinical observation, therefore, highlighted the non-exclusive correlation between GAS6 and AXL in breast cancer progression." (PMID 33182542, 2020). "Exogenous expression of the Sp1 and Sp3 transcription factors can increase AXL transcripts in several cancer cell lines, although this has not been examined in breast cancer." (PMID 32148495, 2020). "AXL activation also impacts immunotherapy and radiotherapy responsiveness in breast cancer, and functions as one of the major contributors to lapatinib resistance in HER2-positive breast cancer." (PMID 32992696, 2020). "Moreover, a MZF1 target gene AXL, which can be activated upon lapatinib resistance in ErbB2 positive breast cancer cells, has been shown to induce EMT in breast cancer cells." (PMID 31963147, 2020). "Analyzing the results described in this review, it is clear that AXL can be a potential marker in which to invest for breast cancer management and not only this, but there is still no solid and definitive evidence on its role in the clinical field." (PMID 33182542, 2020).
breast carcinoma (continued). "Another means by which AXL can promote invasion is through GAS6-mediated phosphorylation of the Elmo scaffold proteins by AXL to ultimately activate Rac GTPase, which also promotes breast cancer cell proliferation." (PMID 32148495, 2020). "AXL is a strong negative predictor of patient survival in breast cancer, indicating its prognostic potential." (PMID 32148495, 2020). "Based on previous studies, we hypothesized that we can decrease the expression of AXL and MET simultaneously by overexpressing miR-34a in breast cancer cell lines." (PMID 30386383, 2018). "Previous studies highlight the role of AXL and MET in breast cancer." (PMID 30386383, 2018). "We selected MDA-MB-231 breast cancer cell line because it similarly expresses YAP and TAZ co-activators, presents a high TEAD transcriptional activity and yields a high expression of gene targets (AXL, Cyr61 and CTGF)." (PMID 29738494, 2018). "We found that AXL was not expressed in normal human breast epithelial MCF-10A cells but was expressed in the two TNBC cell lines of the four breast cancer cell lines we examined." (PMID 29097911, 2017). "We previously showed that KISS1R expression triggered AXL expression in the ERα-negative cells SKBR3 breast cancer cells, which normally do not express AXL." (PMID 28422142, 2017). "Our observations are supported by Li and colleagues, who demonstrated that depletion of AXL in MDA-MB-231 cells decreased PI3K/AKT signaling, resulting in decreased of slug expression; this in turn suppressed breast cancer cell invasion and restored drug sensitivity." (PMID 28422142, 2017). "MERTK is a transmembrane protein of the MER/AXL/TYRO3 receptor tyrosine kinase family, and is also a proto-oncogene that appears upregulated in cancers such as mammary tumours, cell lines from which have been shown to demonstrate an enhanced level of efferocytosis." (PMID 28813472, 2017). "Additionally, in two models of murine breast cancer, treatment with BGB324 blocked known AXL-mediated metastatic functions and synergized with cisplatin, a cytotoxic chemotherapy, to prevent liver micrometastases." (PMID 27834816, 2016). "Collectively, AXL may play a crucial role in resistance to EGFR inhibitors and may represent a critical therapeutic strategy for breast cancer." (PMID 27590506, 2016). "Suppression of AXL by an anti-tumor protein, E1A, enhanced EGFR-TKI (gefitinib, erlotinib and lapatinib) sensitization, resulting in significant inhibition of tumor growth in breast cancer cells." (PMID 27590506, 2016). "In contrast, the primary growth of other tumors such as ovarian, renal cell carcinoma, and breast cancer cells is not affected by AXL inactivation." (PMID 27834845, 2016). "When we examined the data from 172 tumors that were classified as Grade 3, ER negative basal-like breast cancer, a prognostic power of AXL was observed with poorer patient outcomes (p = 0.01)." (PMID 26356563, 2015). "In addition, the significant therapeutic effect of cabozantinib, which targets MET, VEGFR2, and AXL, for bone metastasis in patients with RCC, prostate cancer, and breast cancer also indicates the importance of MET inhibition in the treatment of bone metastasis." (PMID 40299443, 2025). "Similarly, AXL protein expression was notably higher in human TNBC cells and mouse TNBC cell line models, particularly in mesenchymal subtypes compared to other breast cancer cell types." (PMID 41009462, 2025). "In addition, cell line expression data also reveal that high AXL expression is found in drug-resistant breast cancer cells and small-cell lung cancer cells (SCLC), but not in drug-sensitive cells." (PMID 37328828, 2023).